CDK12 (cyclin dependent kinase 12)
Description:
Cyclin-dependent kinase that phosphorylates the C-terminal domain (CTD) of the large subunit of RNA polymerase II (POLR2A), thereby acting as a key regulator of transcription elongation. Regulates the expression of genes involved in DNA repair and is required for the maintenance of genomic stability. Preferentially phosphorylates 'Ser-5' in CTD repeats that are already phosphorylated at 'Ser-7', but can also phosphorylate 'Ser-2'. Required for RNA splicing, possibly by phosphorylating SRSF1/SF2. Involved in regulation of MAP kinase activity, possibly leading to affect the response to estrogen inhibitors.
Synonyms: CrkRS; CRK7; KIAA0904; CRKR
Tractability: Small molecule: a drug acting on it is in phase 2 or 3 trials; a structure with a bound ligand is known; a high-quality ligand is known; it belongs to a druggable protein family. PROTAC: it is named in the literature on targeted protein degradation; UniProt records ubiquitination sites on it; ubiquitination databases record sites on it; its protein half-life has been measured; a small molecule that binds it is known.
Target class: Kinase; Enzyme; CMGC protein kinase CDK family; CMGC protein kinase group; Protein Kinase
Chemical probes: BSJ-01-175 (high quality), BSJ-4-116 (high quality), MFH290 (high quality), SR-4835 (high quality), THZ531 (high quality)
Gene: Protein-coding gene on chromosome 17 (39,461,437 to 39,567,559, forward strand). Ensembl gene ENSG00000167258.
Subcellular location: Nucleus; Nucleus speckle
Subcellular location (Human Protein Atlas): Nuclear speckles; Nucleoplasm
Gene Ontology:
Molecular function: cyclin binding; protein binding; protein kinase activity; RNA polymerase II CTD heptapeptide repeat kinase activity; ATP binding; cyclin-dependent protein serine/threonine kinase activity; protein kinase binding; protein serine kinase activity
Biological process: cellular response to estrogen stimulus; negative regulation of intracellular estrogen receptor signaling pathway; negative regulation of MAPK cascade; positive regulation of transcription by RNA polymerase II; positive regulation of transcription elongation by RNA polymerase II; regulation of MAP kinase activity; transcription by RNA polymerase II; RNA splicing; regulation of cell cycle
Cellular component: cyclin K-CDK12 complex; nuclear speck; nucleoplasm; nucleus; cyclin/CDK positive transcription elongation factor complex; nuclear cyclin-dependent protein kinase holoenzyme complex; cyclin-dependent protein kinase holoenzyme complex
Genetic constraint (gnomAD): Loss-of-function variants: 15 observed, 109.76 expected, observed/expected ratio (o/e) 0.14, 90% interval 0.09 to 0.21. The upper end of that interval is the gene's LOEUF score, 0.21, which puts it in group 1 of 6, group 1 being the genes least tolerant of losing a copy. Missense variants: 1,437 observed, 1,738.4 expected, observed/expected ratio (o/e) 0.83, 90% interval 0.79 to 0.86. Synonymous variants: 652 observed, 662.16 expected, observed/expected ratio (o/e) 0.98, 90% interval 0.92 to 1.05.
Cancer hallmarks: genome instability and mutations (suppresses); change of cellular energetics (promotes)
Homologues: Orthologues: chimpanzee CDK12 (99% identical), macaque CDK12 (98% identical), rabbit CDK12 (96% identical), pig CDK12 (95% identical), dog CDK12 (95% identical), guinea pig CDK12 (93% identical), rat Cdk12 (92% identical), mouse Cdk12 (91% identical), tropical clawed frog cdk12 (67% identical), zebrafish cdk12 (44% identical). Paralogues in human: CDK13 (44% identical), PRP4K (13% identical), CDK11A (13% identical), CDK11B (13% identical), CDK16 (12% identical), CDK17 (12% identical), CDK9 (11% identical), CDK18 (11% identical), CDKL5 (11% identical), CDK14 (10% identical), CDK19 (10% identical), CDK10 (9% identical), and 14 more.
Diseases named in the same sentence as CDK12 in open-access papers:
CDK12 is named in the same sentence as 104 diseases in open-access papers, as found by Europe PMC text mining. Sharing a sentence is not in itself a finding about the gene and the disease. The quoted sentences say what the papers report.
prostate carcinoma (113 papers, 2013 to 2026). A carcinoma that arises from epithelial cells of the prostate gland. "New selective CDK12/13 inhibitors and degraders such as YJ9069 demonstrate efficacy in preclinical models of CDK12-deficient prostate cancer, suggesting opportunities for biomarker-guided therapeutic development." (PMID 41491919, 2026). "Established and emerging biomarkers—such as MSI-H/dMMR status, CDK12 alterations, and tumor mutational burden—hold promise for guiding immunotherapy in prostate cancer." (PMID 40227610, 2025). "In prostate cancer, CDK12 loss defines an immunogenic subtype characterized by neoantigen production and increased sensitivity to immune checkpoint inhibitors, including anti–PD-1 therapy." (PMID 40996961, 2025). "Biallelic loss-of-function mutations in the CDK12 gene are present in primary prostate cancers and more often in metastatic CRPC." (PMID 40163908, 2025). "Together, these results confirm mRNA shortening, the APA activation phenotype, and downregulation of transcripts and proteins involved in HR in prostate cancer models under acute CDK12 loss conditions." (PMID 39071291, 2025). "Accordingly, CDK12 mutations are associated with genomic instability in many cancer types, including prostate cancer." (PMID 40163908, 2025). "In advanced prostate cancer and ovarian cancer, inactivating mutations of CDK12 define distinct molecular subtypes of the disease." (PMID 40955658, 2025). "In prostate cancer, inactivating CDK12 mutations correlates with high genomic instability and aggressive clinical features." (PMID 40166687, 2025). "We previously reported that inactivating mutations in CDK12 were associated with higher levels of intratumoral T cells in advanced prostate cancer." (PMID 40955658, 2025). "CDK12 inactivation has been linked to higher levels of intratumoral T cells in advanced prostate cancer." (PMID 40955658, 2025). "Another study showed that THZ531 preferentially downregulated oncogenic transcripts that are sensitive to CDK12 inhibition and/or associated with super-enhancers, thereby downregulating survival processes in prostate cancer cells." (PMID 40163908, 2025). "Specifically in prostate cancer, biallelic inactivation of CDK12 is associated with a unique genome instability phenotype." (PMID 40149637, 2025). "CDK12‐deficient prostate cancers reprogramme cellular energy metabolism to support their aggressive progression." (PMID 38736108, 2024). "This disruption is particularly detrimental in cancers harboring functional inactivating mutations in CDK12, such as ovarian and prostate cancers, where compromised DDR pathways lead to genomic instability." (PMID 39353441, 2024). "In a study conducted on prostate cancer, CDK12-mutated tumours showed higher T-cell infiltration and more expansion of cloned T cells relative to other prostate cancer genomic subtypes." (PMID 38503865, 2024). "It is surprising to note that the frequency of CDK12 mutations in prostate cancer patients varies considerably based on race and geography." (PMID 38736108, 2024). "CDK12‐deficient CRPC continues to be one of the most challenging subtypes of prostate cancer to treat in clinical practice." (PMID 38736108, 2024). "To seek more efficient treatment drugs for CDK12‐deficient prostate cancer, we examined the response of pan‐cancer cell lines with CDK12 mutations to different medications in the Genomics of Drug Sensitivity in Cancer database." (PMID 38736108, 2024). "We first examined the intracellular levels of ATP and found that more ATP production was observed in CDK12‐deficient prostate cancer cells than in control cells." (PMID 38736108, 2024). "While East Asia has a low incidence of prostate cancer, Chinese prostate cancer patients have one of the highest frequencies of CDK12 mutations globally." (PMID 38736108, 2024). "Cyclin‐dependent kinase 12 (CDK12)‐deficient prostate cancer defines a subtype of castration‐resistant prostate cancer (CRPC) with a poor prognosis." (PMID 38736108, 2024).
prostate carcinoma (continued). "As a result, prostate cancer patients with CDK12 mutations have significantly shorter overall survival than patients without mutations." (PMID 38736108, 2024). "Based on bioinformatics analysis, we evaluated the relationship between CDK12 deficiency and prostate cancer patient's prognosis and treatment resistance." (PMID 38736108, 2024). "As expected, the growth inhibition of prostate cancer cells caused by rotenone significantly increased with CDK12 knockout." (PMID 38736108, 2024). "CDK12 is also the most frequently mutated of all CDKs, reaching up to 5%, and its genomic alterations have been identified in cancers, such as prostate cancer, breast cancer, and colorectal cancer." (PMID 38503865, 2024). "Olaparib can be used to inhibit oncogenic mutations or truncating mutations of CDK12 to reduce the risk of prostate cancer or NOS metastasis." (PMID 37152984, 2023). "We supplemented this knowledge by providing a predictive model of CDK12 deficiency that achieved high accuracy (area under the receiver operator characteristic [AUROC] = 0.97) in prostate cancer." (PMID 36883553, 2023). "CDK12 alterations were found in 6% of advanced prostate cancer in one study, and were typically linked to poor prognosis as well as insensitivity to PARP inhibitors." (PMID 37842236, 2023). "The subset of prostate cancer with CDK12 mutations display more aggressive disease features such as a shorter time to metastasis and development of castration resistant disease." (PMID 36998466, 2023). "CDK12 is associated with tandem duplications, and we here demonstrate that this association can accurately predict gene deficiency in prostate cancers (area under the receiver operator characteristic curve = 0.97)." (PMID 36883553, 2023). "Accordingly, chemotherapy-naïve prostate cancer patients with biallelic CDK12 mutations benefit from PD-L1 checkpoint inhibitors." (PMID 36139513, 2022). "CDK12 mutations in primary and castration-resistant prostate cancer have also been reported, mutually exclusive with other mutations in DNA repair genes." (PMID 35912188, 2022). "Although mutations in most CDKs are rarely observed, CDK12 mutations are observed in different cancer types (2.6% of all cases, enriched in ovarian and prostate cancer) which are often homozygous and lead to a loss function." (PMID 36139513, 2022). "We examined the frequencies of CCND1 and MDM2 copy number gains in cases with CDK12 mutations in the public data on advanced prostate cancer and found these to be 50% and 23%, respectively, which is generally consistent with our data." (PMID 36271301, 2022). "Cyclin-dependent kinase 12 (CDK12) is one of the frequently mutated genes in prostate cancer and sometimes considered one of the DNA-damage response genes." (PMID 36271301, 2022). "From a clinical perspective, biallelic loss-of-function mutations of CDK12 are identified in cancer, and are relatively frequent in ovarian and prostate cancers." (PMID 36139513, 2022). "In prostate cancer, the bi-allelic inactivation of CDK12 is associated with a large number of focal copy-number gains dispersed across the genome." (PMID 35912188, 2022). "In prostate cancer, inactivating CDK12 mutations produces tumor-specific neoantigens and possibly sensitivity to immunotherapy." (PMID 35785167, 2022). "The previous studies have found that there were high-frequency mutation and amplification expression of CDK12 in several malignancies, including ovarian, breast, and prostate cancers." (PMID 33628849, 2021).
prostate carcinoma (continued). "Deleterious CDK12 alterations are enriched from localized to advanced prostate cancers, occurring in 5–11% of patients with mCRPC, and associated with worse prognosis and high Gleason scores." (PMID 33781305, 2021). "Consistent with its role in the maintenance of genome stability, CDK12 that is lost or mutated is associated with the progression and metastasis of a subset of human cancers, including serous ovarian, breast, and prostate cancers." (PMID 32451425, 2020). "Abnormal expression or mutation of CDK12 is detected in various cancers, such as breast cancer, ovarian cancer, prostate cancer and gastric cancer." (PMID 32570740, 2020). "CDK12 biallelic loss is associated with increased immunogenicity due to higher neoantigen burden compared to other molecular subtypes of prostate cancer and is mutually exclusive with mutations in DDR." (PMID 30514390, 2018). "Using genomic analysis of mCRPC samples, recent data has identified a subtype of mutant tumors in advanced prostate cancer with biallelic loss of CDK12." (PMID 30514390, 2018). "CDK12, a cyclin-dependent kinase that directly regulates transcription and controls genomic stability, has been linked to poor prognosis in prostate cancer patients for whom both CDK12 alleles are inactivated, particularly in response to taxane and hormonal therapies." (PMID 40297177, 2025). "It has been suggested that prostate cancer with CDK12 mutations could be sensitive to immune checkpoint inhibitors due to the increased number of fusions; however, this hypothesis has not been confirmed by clinical data." (PMID 41465280, 2025). "To carry out these studies, we developed a new in vitro model of de novo CDK12BAL prostate cancer by generating a cell line (LuCaP189.4_CL) from the LuCaP189.4 patient derived xenograft (PDX) that carries bi-allelic CDK12 frameshift mutations (p.S345Gfs*10, p.S521Qfs*89)." (PMID 39071291, 2025). "Despite this essentiality, a subset of human prostate cancers do tolerate the loss of CDK12." (PMID 39071291, 2025). "Mutations of CDK12 are rare in cancers, other than ovarian cancer and advanced prostate cancer." (PMID 40955658, 2025). "Based on this discordance, we sought to test the hypothesis that an HRd phenotype is primarily a consequence of acute CDK12 loss and the effect is greatly diminished in prostate cancers adapted to CDK12 loss." (PMID 39071291, 2025). "This was expected, as CDK12 mutations have been reported to be early drivers of prostate cancer." (PMID 40824681, 2025). "However, from clinical data, the response rate of CDK12‐mutated prostate cancer patients to PARPi was much lower than that of patients with BRCA2 mutations." (PMID 38736108, 2024). "CDK12‐mutated prostate cancer has been classified as a unique subtype of prostate cancer." (PMID 38736108, 2024). "Interestingly, CDK12 mutant prostate cancers with loss of CDK12 represent a distinct class of prostate cancer." (PMID 39146303, 2024). "In prostate cancer, CDK12 mutations occur in 5%–7% of patients with mCRPC." (PMID 39353441, 2024). "CDK12‐mutated prostate cancer patients also had a higher tumour mutation burden (TMB) than CDK12 wild‐type prostate cancer patients, which leads to an increased generation of neoantigens that may result in a better response to immune therapies." (PMID 38736108, 2024). "It remains unclear, however, whether CDK12 loss per se is sufficient to drive prostate cancer development-either alone, or in the context of other genetic alterations-and whether CDK12-mutant tumors exhibit sensitivity to specific pharmacotherapies." (PMID 38562774, 2024). "Furthermore, targeting the ETC substantially inhibited the proliferation of CDK12‐deficient CRPC cells in vitro and in vivo, suggesting a potential new target for the therapy of CDK12‐deficient prostate cancer." (PMID 38736108, 2024).
prostate carcinoma (continued). "Additionally, mutations in CDK12 in prostate cancer are often accompanied by extensive tandem duplication, an abnormal form of chromosomal rearrangement." (PMID 38736108, 2024). "It remains unclear, however, whether CDK12 loss drives prostate cancer (PCa) development or uncovers pharmacologic vulnerabilities." (PMID 39368479, 2024). "Thus, CDK12‐deficient prostate cancer patients continue to pose a most significant challenge for effective treatment in clinical practice." (PMID 38736108, 2024). "Surprisingly, CDK12 mutation frequency in prostate cancer showed a significantly higher rate in Chinese patients, with 15.4%−27.2% compared to approximately 4.7% among global prostate cancer patients." (PMID 38736108, 2024). "Since immunotherapy and CDK4/6 inhibition are currently in clinical trials for prostate cancer with CDK12 mutations, there will be opportunities in future to determine the extent to which CDK12d classification is associated with disease response to various targeted therapies." (PMID 36914848, 2023). "Similarly, CDK12 loss-of-function mutations in prostate cancer sensitizes the cancer cells to androgen receptor antagonists." (PMID 38132164, 2023). "More recently, CDK12 loss of function alterations was found to be associated with increased focal tandem duplications and greater genome‐wide structural variation in ovarian and prostate cancers." (PMID 34898046, 2022). "Finally, CDK12-mutant associated tandem duplications in prostate cancer are enriched for duplication of cell cycle-related genes, such as MCM7 and CCND1, compared to other tandem duplication phenotypes." (PMID 36139513, 2022). "An important role in cell cycle is carried out by Cyclin-dependent kinase 12 (CDK12), which can be found mutated in a subgroup of prostate cancer patients with infiltration of CD4+forkhead boxP3 (FOXP3)- T-cells and neoantigens exposition, thus resulting in an exalted immunotherapy response." (PMID 35328633, 2022). "A study in 2018 reported that immune checkpoint inhibitors (ICIs) might be efficient for prostate cancer with biallelic CDK12 loss." (PMID 36271301, 2022). "In addition, screening for patients with immunogenic prostate cancer, associated with mutations in mismatch repair and CDK12, is advocated within routine care and for clinical trial participation." (PMID 33327413, 2020). "However, as more clinical data become available, CDK12 mutations in prostate cancer appear to minimally respond to PARPis." (PMID 33233320, 2020). "CDK12 is often mutated in ovarian and prostate cancer and CDK12 deficiency may thus prove useful as a biomarker of PARP inhibitor response." (PMID 32029455, 2020). "Inactivating CDK12 alterations have been reported in ovarian and prostate cancers; however, the prevalence of these mutations across all cancer types is unknown." (PMID 31360735, 2019). "Furthermore, it was reported that CDK12 loss in prostate cancer was associated with genomic instability and tandem duplication which leaded to increased T cell infiltration." (PMID 31523177, 2019). "Of major importance are two recent studies that demonstrate/confirm CDK12 is a tumor suppressor for ovarian and prostate cancers and go on to show that bi-allelic loss of CDK12 in ovarian or prostate tumor cells leads to large numbers of tandem duplications spread throughout the genome." (PMID 31652541, 2019). "Recently, in prostate cancer, CDK12 biallelic inactivating mutation was significantly correlated with T cells infiltration and identified a novel subtype of metastatic castration-resistant prostate cancer with high sensitivity to immune checkpoint inhibition." (PMID 31523177, 2019). "In fact, CDK12-variant tumors display higher overall levels of T cell infiltrating lymphocytes and greater numbers of expanded T cell clones than other prostate cancer subtypes; furthermore, these tumors display also increased expression of some chemokines and their receptors." (PMID 31366128, 2019).